ARL2BP (ARF like GTPase 2 binding protein)
Description:
Together with ARL2, plays a role in the nuclear translocation, retention and transcriptional activity of STAT3. May play a role as an effector of ARL2.
Synonyms: BART; BART1; RP66; RP82
Tractability: Small molecule: a structure with a bound ligand is known. PROTAC: ubiquitination databases record sites on it; its protein half-life has been measured.
Gene: Protein-coding gene on chromosome 16 (57,245,259 to 57,253,635, forward strand). Ensembl gene ENSG00000102931.
Subcellular location: Cytoplasm; Mitochondrion intermembrane space; Cytoplasm, cytoskeleton, microtubule organizing center, centrosome; Nucleus; Cytoplasm, cytoskeleton, spindle; Cytoplasm, cytoskeleton, cilium basal body
Subcellular location (Human Protein Atlas): Cytosol; Nucleoplasm; Basal body; Centrosome
Pathways (Reactome):
Transport of small molecules: Transport of nucleosides and free purine and pyrimidine bases across the plasma membrane
Gene Ontology:
Molecular function: protein binding; transcription coactivator activity; GTPase regulator activity
Biological process: maintenance of protein location in nucleus; positive regulation of tyrosine phosphorylation of STAT protein; signal transduction; positive regulation of DNA-templated transcription
Cellular component: centrosome; ciliary basal body; midbody; mitochondrial intermembrane space; nucleoplasm; cytosol; mitochondrial matrix; cytoplasm; nucleus; spindle
Genetic constraint (gnomAD): Loss-of-function variants: 10 observed, 16.46 expected, observed/expected ratio (o/e) 0.61, 90% interval 0.37 to 1.03. The upper end of that interval is the gene's LOEUF score, 1.03, which puts it in group 4 of 6, group 1 being the genes least tolerant of losing a copy. Missense variants: 134 observed, 156.89 expected, observed/expected ratio (o/e) 0.85, 90% interval 0.74 to 0.99. Synonymous variants: 44 observed, 59.42 expected, observed/expected ratio (o/e) 0.74, 90% interval 0.58 to 0.95.
Gene-disease validity (ClinGen):
ClinGen rates the evidence that ARL2BP causes each of these diseases.
ciliopathy (autosomal recessive): Definitive. A genetic disorder of the cellular cilia or the cilia anchoring structures, the basal bodies, or of ciliary function.
Homologues: Orthologues: chimpanzee ARL2BP (100% identical), pig ARL2BP (96% identical), rabbit ARL2BP (96% identical), mouse Arl2bp (96% identical), guinea pig Arl2bp (94% identical), rat Arl2bp (89% identical), macaque ARL2BP (83% identical), tropical clawed frog arl2bp (72% identical), zebrafish arl2bp (67% identical).
Diseases named in the same sentence as ARL2BP in open-access papers:
ARL2BP is named in the same sentence as 41 diseases in open-access papers, as found by Europe PMC text mining. Sharing a sentence is not in itself a finding about the gene and the disease. The quoted sentences say what the papers report.
ciliopathies (4 papers, 2019 to 2025). "ARL2BP is vital for maintaining cilia structure and sperm flagella, with its deficiency leading to syndromic ciliopathies." (PMID 40432967, 2025). "Our results suggest that ARL2BP is required for the structural maintenance of cilia as well as of the sperm flagellum, and that its deficiency leads to syndromic ciliopathy." (PMID 31425546, 2019). "In this study, we have identified multiple ciliopathy phenotypes associated with mutations in ARL2BP in human patients and in a mouse knockout model." (PMID 31425546, 2019). "Remarkably, CFAP20 interacts with disease-causing proteins including: (i) ARL2BP, associated with RP, (ii) TBC1D32 and FOXJ1, related with ciliopathies, and (iii) LRRK2 and DICER1, involved in retinal degeneration in animal models." (PMID 35246562, 2022).
retinitis pigmentosa (3 papers, 2018 to 2025). Retinitis pigmentosa (RP) is an inherited retinal dystrophy leading to progressive loss of the photoreceptors and retinal pigment epithelium and resulting in blindness usually after several decades. "ARL2BP is linked to retinitis pigmentosa and is essential for the maintenance and function of normal photoreceptors." (PMID 40432967, 2025). "In three unrelated families, variants of ARL2BP have been reported as potential causes of retinitis pigmentosa and may also be associated with organ laterality defects." (PMID 40432967, 2025).
male infertility (2 papers, 2019 to 2025). The inability of the male to effect fertilization of an ovum after a specified period of unprotected intercourse. "In this study, we report the identification of two homozygous mutations in the gene ARL2BP in three Portuguese patients from two consanguineous families displaying RP and male infertility." (PMID 31425546, 2019). "Mutations in ARL2BP cause syndromic male infertility in humans and mice." (PMID 31425546, 2019).
rod-cone dystrophies (2 papers, 2024 to 2025). "Mutations in ARL2BP can cause recessive rod-cone dystrophies." (PMID 40432967, 2025).
situs inversus (2 papers, 2019 to 2024). A congenital condition in which there is complete right-to-left reversal of the position of the major thoracic and abdominal organs (that is, they are arranged in a mirror image of the normal positioning). "This could also explain why only one patient identified with ARL2BP mutations possesses situs inversus, while the incidence in the mouse model is much higher." (PMID 31425546, 2019). "However, a previous study identified one patient with a mutation in ARL2BP with situs inversus." (PMID 31425546, 2019). "In mice, this phenotype is highly penetrant, as most Arl2bp KO animals exhibit situs inversus (55%), with 28% possessing heterotaxy of either the heart or stomach." (PMID 31425546, 2019). "The association of ARL2BP mutations in humans with situs inversus is variable, and the patients reported in this study did not possess situs inversus." (PMID 31425546, 2019). "To date, one patient with defective ARL2BP was reported to have situs inversus." (PMID 31425546, 2019). "Among the genes potentially causative of ciliopathies when altered, biallelic pathogenic variants in ARL2BP (OMIM *615,407) can cause autosomal recessive Retinitis Pigmentosa (arRP) with or without situs inversus (OMIM #615,434)." (PMID 38649918, 2024).
autosomal recessive retinitis pigmentosa (1 paper, 2025). Autosomal recessive retinitis pigmentosa (RP) is an autosomally recessive inherited retinal dystrophy leading to progressive loss of the photoreceptors and retinal pigment epithelium and resulting in blindness usually after several decades. "Homozygous mutations in ARL2BP can lead to autosomal recessive retinitis pigmentosa." (PMID 40432967, 2025).
Blindness (1 paper, 2019). Blindness is the condition of lacking visual perception defined as a profound reduction in visual perception. "Concurrent with the identification of the male patient, we discovered that male Arl2bp KO mice were infertile, as they were not yielding any litters during the generation of the murine Arl2bp KO model to study blindness." (PMID 31425546, 2019).
female infertility (1 paper, 2019). Diminished or absent ability of a female to achieve conception. "Patients with mutations in ARL2BP were not reported to have any symptoms related to defects in these cilia (sinusitis, otitis media, hydrocephaly, or female infertility)." (PMID 31425546, 2019).
hydrocephaly (1 paper, 2019). "Additionally, there was no noticeable difference in the cerebral aqueduct or fourth ventricle between WT and Arl2bp KO mice, nor was there any sign of obstruction in the cerebral aqueduct or fourth ventricle, a common cause of hydrocephaly." (PMID 31425546, 2019).
lung carcinoma (1 paper, 2025). "Our functional experiments inhibiting these genes showed that loss of Ptgds, Arl2bp, Rnf157, and Syt11 can block lung cancer sphere formation." (PMID 40047406, 2025).
renal agenesis (1 paper, 2024). Renal agenesis (RA) is a form of renal tract malformation characterized by the complete absence of development of one or both kidneys (unilateral RA or bilateral RA respectively), accompanied by absent ureter(s). "The presence of renal agenesis and cryptorchidism expands the clinical manifestations due to ARL2BP variants." (PMID 38649918, 2024).
Stroke (1 paper, 2025). Sudden impairment of blood flow to a part of the brain due to occlusion or rupture of an artery to the brain. "For Stroke, there were 3,221 genes and 458 proteins, with 57 overlapping targets at the gene-protein level including ABO, AOC1, and ARL2BP." (PMID 41340073, 2025).
tumor (5 papers, 2018 to 2025). "To test whether these genes regulate tumor cell growth we knocked down each of these genes (Ptgds, Arl2bp, Rnf157, and Syt11) in the KP cell line." (PMID 40047406, 2025).
infection (1 paper, 2019). The state of being infected such as from the introduction of a foreign agent such as serum, vaccine, antigenic substance or organism. "Gene expression differences for Arl2bp and Phc2 were confirmed by RT-PCR on MLN samples at day 5 of infection of wild-type and MIF-deficient mice." (PMID 31708913, 2019).
ARL2BP also shares sentences with these, for which no sentence is quoted: nasopharyngeal carcinoma (5 papers); asthenozoospermia (1); Ataxia (1); autosomal recessive rod-cone dystrophy (1); Burkitt lymphoma (1); cancer (1); gastric cancer (1); glioma (1); hearing loss (1); Hodgkins lymphoma (1); infertile (1); Jalili syndrome (1); Kaposi's sarcoma (1); Kearns-Sayre syndrome (1); lymphoma (1); mitochondrial DNA depletion syndrome (1); Neurodegeneration (1); neuropathy (1); non-Hodgkin lymphoma (1); otitis media (1); pancreatic cancer (1); pantothenate kinase-associated neurodegeneration (1); polyneuropathy (1); primary effusion lymphoma (1); retinal degeneration (1); sinusitis (1); stomach tumor (1).